HTR2A (5-hydroxytryptamine receptor 2A)
Diseases named in the same sentence as HTR2A in open-access papers (continued):
Sharing a sentence is not in itself a finding about the gene and the disease.
brain injury (1 paper, 2026). Acute and chronic (see also brain INJURIES, CHRONIC) injuries to the brain, including the cerebral hemispheres, CEREBELLUM, and brain STEM. "Neurotransmission-related genes (BDNF, COMT, DRD1–3, DBH, SLC6A4, HTR2A, APOE) influenced motivation, fatigue, cognitive performance, and brain injury recovery." (PMID 41596414, 2026).
complex regional pain syndrome (1 paper, 2019). A chronic pain syndrome characterized by a disproportionate spontaneous or stimulus-induced pain, accompanied by a variably mixed myriad of autonomic and motor disorders including symptoms such as swelling, allodynia, skin blood supply and trophic disturbances. "There is a network centered on GNG7, that may be involved in connectivity/signaling, comprising HTR2A, EDN1, PNOC (involved in pain signaling) and CALCA (involved in Reflex Sympathetic Dystrophy and Complex Regional Pain Syndrome)." (PMID 30755720, 2019).
conduct disorder (1 paper, 2024). A disorder diagnosed in childhood or adolescence age group characterized by aggressive behavior, deceitfulness, destruction of property or violation of rules that is persistent and repetitive, and within a one year period. "Furthermore, four SNPs of the 5-hydroxytryptamine receptor 2 A (HTR2A) gene that encodes for one of the receptors for serotonin failed to have a significant difference between the conduct disorder cases and controls in adolescents." (PMID 38862490, 2024).
Constipation (1 paper, 2021). Infrequent or difficult evacuation of feces. "Three genes, 5-HT receptor subtype 2a and 2c (Htr2a and Htr2c) and Transient receptor potential vanilloid 2 (Trpv2) were significantly upregulated in the constipation group in comparison to the control group." (PMID 33441874, 2021). "A significant upregulation of serotonin receptors, Htr2a and Htr2c, was observed in the bladders from mice with constipation, paralleled with augmented spontaneous contractions after pre-incubation of the bladder strips with 0.5 μM of serotonin." (PMID 33441874, 2021). "By contrast, the Htr2a IR was more robust in the constipation group than that in the control group." (PMID 33441874, 2021).
delirium (1 paper, 2020). A disorder characterized by confusion; inattentiveness; disorientation; illusions; hallucinations; agitation; and in some instances autonomic nervous system overactivity. "The misregulation of the four HAR-Brain genes, namely APP, PLCB1, NPY, and HTR2A, in the M1 module is more likely to underlie delirium susceptibility rather than specifically be the molecular pathways driving the development of delirium." (PMID 33086708, 2020). "We found that four of the HAR-Brain genes, namely APP, PLCB1, NPY, and HTR2A, in the M1 module were highly connected and appeared to exhibit hub properties, which might play vital roles in delirium development." (PMID 33086708, 2020).
eating disorder (1 paper, 2022). A broad group of psychological disorders with abnormal eating behaviors leading to physiological effects from overeating or insufficient food intake. "Indeed, specific polymorphisms of the HTR2A gene (homologous to Drosophila 5-HT2A), are associated with altered nutrient preferences, metabolic diseases, and eating disorders." (PMID 36531741, 2022).
enteritis (1 paper, 2024). Inflammation of the small intestine. "Enteritis that is chemically induced by DSS or acetic acid has been associated with the activation of pro-inflammatory HTRs such as HTR2A and HTR7." (PMID 38398793, 2024).
glioblastoma (1 paper, 2025). The most malignant astrocytic tumor (WHO grade IV). "Similarly, primary glioblastoma patient samples exhibited high HTR2A expression, predominantly clustering with malignant OPC- and AC-like states." (PMID 41427306, 2025).
iron deficiency (1 paper, 2016). "In addition to the decreased HTR2A and increased HTR2C expression was observed in the iron deficient hippocampus, a high number of DM CpG sites were associated with HTR2C, suggesting this gene is epigenetically regulated in response to early life iron deficiency." (PMID 27809765, 2016).
lipid metabolism disorder (1 paper, 2020). "Collectively, PPARγ2 is required for the activation of HTR2A-induced lipid metabolism disorder in the liver tissue." (PMID 32477107, 2020).
low grade glioma (1 paper, 2023). A grade I or grade II glioma arising from the central nervous system. "It was found that the expression of HTR2A was high in 3 tumor types (supratentorial ependymomas [STES], pan-kidney [KIPAN], stomach adenocarcinoma [STAD]), predicting poor prognosis; however, it was poorly expressed in 2 tumor types (GBMLGG, low-grade glioma [LGG]) predicting the poor prognosis." (PMID 37564635, 2023).
lung adenocarcinoma (1 paper, 2024). A carcinoma that arises from the lung and is characterized by the presence of malignant glandular epithelial cells. "Additionally, the expression of HTR2A/2B/7 was correlated significantly with immune cells and immune checkpoint genes in a variety of cancers, such as BRCA, brain lower-grade glioma, and lung adenocarcinoma." (PMID 39766808, 2024).
lymphoid cancer (1 paper, 2024). "While cell lines from certain tissues seem to be equally inhibited by top GPCR drugs (e.g., lung), others are sensitive to specific GPCR drugs, such as lymphoid cancer cells, which are particularly inhibited by DRD2, CHRM1, CHRM2, HTR1A, and HTR2A antagonists." (PMID 38723607, 2024).
melanin metabolism disorder (1 paper, 2022). "Furthermore, targeting HTR2A is a potential method to develop drugs for skin diseases with melanin metabolism disorder." (PMID 35682806, 2022).
Myocardial fibrosis (1 paper, 2024). "The 5-HT-induced myocardial fibrosis was increased in Htr2b null mice but not in Htr2a null or Htr2a/2b double null mice." (PMID 39423037, 2024).
prostate carcinoma (1 paper, 2024). A carcinoma that arises from epithelial cells of the prostate gland. "Among these, HTR2A and HTR2B were positively associated with lethal prostate cancer, while HTR6 was inversely associated." (PMID 38995644, 2024).
psoriasis (1 paper, 2024). An autoimmune condition characterized by red, well-delineated plaques with silvery scales that are usually on the extensor surfaces and scalp. "The figure shows that after accounting for known up- and down-regulation expression patterns in psoriasis, only at the endpoint TNFAIP3, SHOC2 and HTR2A expression is retained." (PMID 39337694, 2024).
stomach cancer (1 paper, 2024). "Research has identified serotonin receptors, specifically HTR2A, HTR2B, HTR3A, and HTR7, as potential targets for both the prevention and treatment of stomach cancer." (PMID 39766808, 2024).
psychiatric disorder (20 papers, 2009 to 2025). A disorder characterized by behavioral and/or psychological abnormalities, often accompanied by physical symptoms. "Genetic variants and methylation alterations in HTR2A have been shown to have a significant role in various psychiatric disorders." (PMID 36561742, 2022). "HTR2A primarily encodes the G protein-coupled serotonin 5-HT2A receptor, and the 5-HT/serotonin receptor system has been shown to be associated with inflammatory responses in addition to psychiatric disorders." (PMID 36561742, 2022).
cancer (11 papers, 2015 to 2025). A tumor composed of atypical neoplastic, often pleomorphic cells that invade other tissues. "HTR2A expression was strongly linked with immune infiltration in 25 cancers, of which 21 were significantly positively associated, and 4 were significantly negatively associated." (PMID 37564635, 2023). "High expression of HTR2A in pan-cancer was mainly related to poor OS in KICH and LUSC while being related to better OS in GBMLGG and LGG." (PMID 39766808, 2024). "Therefore, this study aims to delineate the association between SCZ-related genes (HTR2A, COMT, PRODH) and different cancers." (PMID 37564635, 2023). "This study observed significant upregulation of HTR2A in 7 cancers (GBMLGG、LGG、STES、STAD、PAAD、ALL、LAML) and significant downregulation in 22 cancers (GBM、UCEC、BRCA、CESC、LUAD、ESCA、KIRP、KIPAN、COAD、COADREAD、PRAD、LUSC、LIHC、SKCM、BLCA、THCA、READ、OV、TGCT、UCS、ACC、KICH)." (PMID 37564635, 2023). "Therefore, HTR2A activation may become a novel therapeutic strategy to prevent and treat cancer metastasis." (PMID 37795441, 2023). "This study explored the expression of SCZ-related genes (HTR2A, COMT, and PRODH) in pan-cancer analysis." (PMID 37564635, 2023). "Taken together, these findings suggest that HTR2A inhibition could suppress the cytotoxic killing effects of CD8+ T cells and result in cancer metastasis." (PMID 37795441, 2023). "Herein, a preliminary conclusion could be reached that the effect of SCZ-related genes HTR2A, COMT, and PRODH was highly variable in different cancers, and the prognostic significance of SCZ on cancer development needed to be explicitly explored for various cancers." (PMID 37564635, 2023).
tumor (11 papers, 2019 to 2025). "The expression of HTR2A might positively indicate the degree of tumor heterogeneity through MATH and further affect the survival and prognosis of patients." (PMID 37564635, 2023). "In addition, TUNEL staining also confirmed that HTR2A inhibitor reduced the apoptosis of tumor cells." (PMID 37795441, 2023). "The expression of HTR2A may contribute to the degree of tumor heterogeneity through MATH, as well as affecting the patient’s prognosis and survival." (PMID 37564635, 2023). "Besides, HTR2A inhibitor significantly suppressed the expression level of HTR2A on CD8+ T cells in tumor tissues." (PMID 37795441, 2023). "Interestingly in our study, the HTR2B paralog gene HTR2A is substantially expressed in the boundary of the tumour." (PMID 35408449, 2022). "Increases in GnRH exposure could then allow for tumor proliferation, partially by increasing htr2a expression, thus leading to a positive feedback growth response upon subsequent exposure to enteric 5HT." (PMID 30777054, 2019). "Additionally, HTR2A expression may positively correlate with tumor heterogeneity and have an impact on patient prognosis and survival." (PMID 38003496, 2023). "Among these 5-HTRs, HTR7, HTR2A, HTR2B, and HTR2C were extensively studied in different tumor tissues." (PMID 37795441, 2023). "However, 5-NL also has affinity for other HTR receptors also expressed by tumor cells in our system namely HTR1A-B, HTR2A and HTR2C." (PMID 37582744, 2023). "Moreover, HTR2A had high expression in three tumor types (STES, KIPAN, and STAD) with poor prognosis and had low expression in two tumor types (GBMLGG, LGG) with poor prognosis." (PMID 37564635, 2023). "Taken together, we surmise that 5-NL mediated improved anti-tumor immunity occurred irrespective of signaling through receptors HTR1Dβ and HTR2A." (PMID 37582744, 2023).
neurological disorders (9 papers, 2017 to 2025). "To elucidate the pathogenesis of the neurological diseases associated with 5-HT2AR gene (HTR2A) variants, we have previously established a protocol to induce HTR2A-expressing neurons from human-induced pluripotent stem cells (hiPSCs)." (PMID 34326453, 2021). "In conclusion, our in vitro monitoring system allowed the identification and functional analysis of HTR2A-positive neurons induced from hiPSCs, which could be used to elucidate the pathophysiological mechanism of various neurological diseases associated with genetic variations of the HTR2A gene." (PMID 34326453, 2021). "It has been recognized that HTR2A plays a crucial role in orchestration of neurological disorders, so its agonists hold therapeutic potential in neurological disorders." (PMID 35710537, 2022). "The alteration in mRNA levels of Htr2a, Htr4, Htr7, Htr5b, Htr6, and Htr3 indicate that serotonin may increase the risk of CJL mediated neurological disorders." (PMID 36582489, 2022).
cardiovascular disease (4 papers, 2016 to 2022). "Also, the function of the HTR2A-encoded protein is associated with blood pressure and heart rate and is a contributing factor to cardiovascular disease in humans." (PMID 30056651, 2019).
metabolic disease (3 papers, 2022 to 2026). A congenital disorder (due to inherited enzyme abnormality) or acquired (due to failure of a metabolically important organ) disorder resulting from an abnormal metabolic process. "In adulthood, abnormal function of HTR2A has been associated with neuropsychiatric, cardiovascular, and metabolic diseases." (PMID 35203678, 2022). "The findings may contribute to a better understanding of the early developmental origins of neurobehavioral and metabolic disorders associated with altered HTR2A function." (PMID 35203678, 2022). "In addition, the results may contribute to a better understanding of the early developmental causes of neurobehavioral and metabolic disorders associated with altered HTR2A function." (PMID 35203678, 2022).
HTR2A also shares sentences with these, for which no sentence is quoted: Parkinson (12 papers); epilepsy (9); alcohol dependence (6); Delusion (6); diabetes (6); Hallucinations (6); autism spectrum disorder (5); sexual dysfunction (5); atherosclerosis (4); dementia (4); infection (4); pulmonary hypertension (4); serotonin syndrome (4); alcohol (3); Anorexia (3); anxiety disorder (3); behavioral disorders (3); heart failure (3); liver fibrosis (3); pulmonary fibrosis (3); Visual hallucination (3); Abdominal obesity (2); colitis (2); diabetic neuropathy (2); Dyskinesia (2); emotional dysregulation (2); fragile X syndrome (2); Hyperinsulinemia (2); hyperprolactinaemia (2); itch (2).
A further 95 diseases each share a sentence with HTR2A in 2 papers or fewer.